SALL4 (spalt like transcription factor 4)
Diseases named in the same sentence as SALL4 in open-access papers (continued):
Sharing a sentence is not in itself a finding about the gene and the disease.
tumor (continued). "In addition, in tumor samples without invasion to adventitia (T1, T2), SALL4 gene expression significantly correlated with patients’ ages (P = 0.033, correlation coefficient: -0.967)." (PMID 23363002, 2013). "Therefore, we aimed in the current study to evaluate the expression of LINC-ROR in tumor and adjacent non-cancerous tissues of GC patients and to investigate its probable linkage with SALL4 stemness regulator, as well as their correlation with clinicopathological features of patients." (PMID 33745265, 2021). "The expression of Sall4 in fetal liver but not in adult liver, and importantly, re-expression in tumor liver led us to hypothesize that SALL4 might be an important mediator in HBV-induced PD-L1 expression which attributes to the immune tolerance for development and progression of HCC in adulthood." (PMID 29593314, 2018). "The tumor cells of case 1 showed negative staining for PCK, EMA and CK7, diffuse positivity for SALL4 and Syn." (PMID 38877473, 2024). "The tumor cells of case 2 was negative expression of PCK, EMA and CK7, diffuse positivity for SALL4 and partial positivity for Syn." (PMID 38877473, 2024). "The tumor cells of the adenocarcinoma component had periodic acid-Schiff (PAS)-positive globules and were positive for sal-like protein 4 (SALL 4) and negative for α-fetoprotein (AFP) or human epidermal growth factor receptor type 2 (HER2)." (PMID 31960152, 2020). "At immunohistochemical analysis, both tumor components were negative for germ cell markers (AFP, SALL4, and Glypican-3), while they showed distinctive expression of Müllerian and intestinal markers." (PMID 32781666, 2020). "Immunohistochemical analysis revealed that the tumor cells were positive for CD21, CD35 and CXCL-13, focal positive for CD23, while negative for D2–40, CK, P63, CD30, SALL4, PLAP, EBV-LMP-1." (PMID 30646936, 2019). "We found that transfection of SALL1, but not SALL4 or vector in MCF-7, MDA-MB-231, E0771 and PC-3 tumor cells significantly inhibited cell growth and proliferation." (PMID 29625565, 2018). "The tumor cells stained positive for AFP and Sal-like protein 4 (SALL4), but were negative for carcinoembryonic antigen, synaptophysin, chromogranin A, and neural cell adhesion molecule." (PMID 28545511, 2017). "On immunohistochemistry, the tumor cells were positive for S100P and SOX-10 and focally positive for HMB-45 and Melan A. Tumor cells were negative for CK, EMA, SMA, TTF1, PAX8, GATA3 and SALL4." (PMID 38509523, 2024). "The tumor cells were negative for AE1/3, Cam5.2, CKIT, DOG1, CD99, SOX10, S100, HMB45, MelanA, Syn, CgA, Trypsin, Desmin, SMA, Caldesmon, collagen type 4, Laminin, Inhibin, Calretinin, STAT6, CD34, ERG, WT1, ER, PR, and SALL4." (PMID 36928336, 2023). "However, the moderate staining of CK8 and SALL-4, and the focal staining of S-100, p40 and CK20 in the primary tumor, were completely absent in the cell line." (PMID 38201285, 2023). "On the other hand, negative correlation of EZH2 (r = -0.53, p < 0.001), SALL4 (r = -0.4, p < 0.001), TCF3 (r = -0.45, p < 0.001) with Hp in high tumor Hp expression group could also be an indication of relative well cancer differentiation." (PMID 28158312, 2017). "The SALL4 positive immunoreactivity was detected in a total of 102 ICC cases (58%), and non-reactivity was validated on tissue sections from 73 cases (42%), whereas non-reactivity was observed on total 28 adjacent non-tumor tissues." (PMID 26317546, 2015). "There were also significant correlations between concomitant mRNA expression of SALL4 and LINC-ROR in tumors located at distal noncardiac, positive for H.pylori infection, tumors with invasion into the muscle layer of the stomach, and grade II tumor (p < 0.05)." (PMID 33745265, 2021).
tumor (continued). "Here we elucidated the correlation between MEIS1 and stemness marker SALL4 in ESCC and revealed significant correlation between the genes in different early pathological features of the disease including non-invaded state, at primary stages of tumor progression." (PMID 32819319, 2020).
cancer (124 papers, 2008 to 2025). A tumor composed of atypical neoplastic, often pleomorphic cells that invade other tissues. "Clinically, SALL4 overexpression is associated with aggressive disease and poor prognosis in several cancers." (PMID 41163374, 2025). "Despite its characterization as a biomarker in various cancers, the role of SALL4 in GIT cancers and the underlying mechanisms are unclear." (PMID 38584262, 2024). "Similar to mice, the expression of SALL4 is downregulated during development and rarely detectable in human adult tissues, but when reactivated it is a leading cause of a wide spectrum of cancers." (PMID 38062245, 2024). "Here we reviewed the major molecular mechanisms associated with SALL4 in different cancers and also extensively went through the drugs designed against SALL4 and its interactions." (PMID 36010677, 2022). "One potential cause of aberrant expression of SALL4 in cancer cells is DNA hypomethylation at CpG islands." (PMID 36010677, 2022). "Our findings indicate that SALL4 is associated with clinicopathological features related to cancer progression in GC and its function in the Wnt/β-catenin pathway." (PMID 33644042, 2021). "SALL4 expression in carcinoma cells was recently reported, and SALL4 was suggested to be associated with cell proliferation and epithelial–mesenchymal transition (EMT)." (PMID 34441397, 2021). "In line with the results of TCGA dataset analysis (Fig EV3D), p‐TFCP2L1 expression was more associated with cancer‐specific survival than SALL4 or CD44 expression in the BC patient cohort." (PMID 31709755, 2020). "For instance, SALL4 has been verified to be associated with cell migration, metastasis, invasion, drug resistance in these cancers." (PMID 31888172, 2019). "We aimed at investigating the risk associated with SALL4 reactivation for all-cause mortality and recurrence in cancer using the current literature." (PMID 28160555, 2017). "Results showed that the expression of SALL4 was significantly associated with increased cancer mortality and recurrence, also after adjusting for potential confounders in the survival analyses." (PMID 28160555, 2017). "There were several functional associations between SALL4 and cancer incidence, progression, and subsequent metastasis, suggesting that this molecular marker could be effective in eradicating malignant cells." (PMID 39001344, 2024). "Restored SALL4 expression has been found in various tumors and linked to cancer progression." (PMID 37525212, 2023). "In addition, it was demonstrated that the anti-apoptotic protein Bcl2 is upregulated in SALL4 transgenic mice, causing more cancer cell survival." (PMID 36010677, 2022). "Expression of MEIS1 was associated with SALL4 in poorly differentiated cancer cells." (PMID 35216168, 2022). "This study, which included a larger series of 1,815 patients, reported that 16.7% of GC tumors were SALL4-positive and that SALL4 positivity was associated with cancer progression-related clinicopathologic parameters, such as advanced stage, lymph node metastasis, and vascular invasion." (PMID 33644042, 2021). "SALL4 is the most well studied SALL gene‏ associated with the cancer s." (PMID 28959334, 2016). "Collectively, SALL4 exemplifies remarkable regulatory versatility, offering valuable insights into both developmental biology and cancer therapies." (PMID 39936946, 2025). "In summary, these studies represent a new approach for IMiD independent drug discovery targeting C2H2 transcription factors such as SALL4 in cancer." (PMID 40369156, 2025). "The top cancer genes with recurrent variants included: STAT2 (33%), DMNT1 (27%), HSP90AA1 (17%), CDK4, NOTCH2, THRAP3, and SALL4 (13% each)." (PMID 41353477, 2025).
cancer (continued). "Considering the inherent instability of cancer cells, aberrant SALL4 expression has been reported in both solid tissues and hematologic malignancies." (PMID 39905414, 2025). "SALL4 has been identified as playing a crucial role in maintaining stemness, regulating angiogenesis, and modulating cancer-related pathways such as Wnt/β-catenin and VEGF signaling." (PMID 39905414, 2025). "Cancer stemness is recognized by the presence of stemness-related markers in human cancers such as Oct4, Sox2, Klf4, c-Myc, Sall4, and Nanog." (PMID 40076435, 2025). "SALL4, a cancer driver, contains seven C2H2 zinc fingers in three clusters, including an IMiD degron in zinc finger cluster one (ZFC1)." (PMID 40369156, 2025). "In these contexts, SALL4 plays crucial roles in promoting cancer cell survival, proliferation, metastasis, and therapy resistance." (PMID 41163374, 2025). "In consideration of this, the binding of 3-MP to human cereblon, together with its potential to reduce the expression of SALL-4 in Tera-1 cells (a human immortalized carcinoma line) were evaluated, using Pom as a positive control." (PMID 40524167, 2025). "Both the serum level and immunohistochemical expression of AFP can be used to indicate the poor prognosis for gastric adenocarcinoma, while the SALL4 immunohistochemistry can also be an indicator of adverse prognosis for such cancer." (PMID 38584262, 2024). "In HCC-derived exosomes, SALL4 regulates M2 polarization and miR-146a-5p expression, which promotes cancer progression." (PMID 38584262, 2024). "We describe the functions of SALL4 in GIT cancers and discuss its upstream/downstream genes and pathways associated with each cancer." (PMID 38584262, 2024). "The recent discovery that the small immunomodulatory drug thalidomide induces ubiquitylation and degradation of SALL4 by the CRL4CRBN E3 ubiquitin ligase has demonstrated that this transcription factor can be targeted for cancer therapy." (PMID 38062245, 2024). "Activated SALL4 enhances spheroid formation, invasion capacities, and key characteristics of cancer stem cells while upregulating the EMT markers, hepatic stem cell markers KRT19, EpCAM, and CD44, in hepatocyte cell lines." (PMID 38584262, 2024). "Another study has shown that the SALL4 gene is more frequently hypermethylated in aneuploid cancers (8 of 16, 50%) than in diploid cancers (3 of 18, 17%)." (PMID 38584262, 2024). "SALL4 plays a vital role in regulating the cell cycle and apoptosis, as well as in the formation and development of malignant tumors, but its role in different tumors is regulated by different mechanisms." (PMID 38584262, 2024). "This review shows that SALL4 participates not only in the growth, anti-apoptosis, metastasis, and invasion of these cancers but also in drug resistance, EMT, OXPHOS, DNA methylation and angiogenesis, in some cases." (PMID 38584262, 2024). "Spalt-like protein 4 (SALL4) is a stemness-related transcription factor whose abnormal re-expression contributes to cancer initiation and progression." (PMID 37525212, 2023). "SALL4 is an unfavorable predictor of survival expectancy, drug resistance, and metastasis in many cancer subsets." (PMID 36587397, 2023). "Co-delivery of the functional siRNA and anticancer drug via exosomes represents a useful approach to inhibiting cancer angiogenesis by targeting SALL4/VEGF pathway." (PMID 37525212, 2023). "Gene expression analyses revealed that the SALL4‐related molecular network defines a PDAC subset enriched in cancer stem cell functions and stromal organization." (PMID 36587397, 2023). "We established that SALL4 correlated with PDAC stemness properties and the presence of cancer‐associated fibroblasts (CAF) activated by TGF‐β." (PMID 36587397, 2023). "Targeting SALL4 has a promising therapeutic effect on cancer and has the potential to become an effective therapeutic strategy." (PMID 37525212, 2023).
cancer (continued). "Numerous studies demonstrate that SALL4 plays a key role in carcinogenesis, cancer metastasis, and cancer therapy resistance." (PMID 37525212, 2023). "Altogether, these results highlight that TGF‐β1 signaling in cancer stroma interacts with SALL4 transcriptional activity to promote PDAC oncogenic properties." (PMID 36587397, 2023). "Sall4-NuRD interaction has been reported in cancer and in development processes such as hematopoiesis and neurogenesis." (PMID 37208322, 2023). "SALL4 as a cancer stem cell related gene, is suggested as a valuable prognostic biomarker for classification of progenitor-like HCC subtypes." (PMID 36010677, 2022). "The epigenetic modifications also affect SALL4 expression through the CpG island located at the Exon 1/Intron 1 region and reported to be hypomethylated both in embryonic stem cell and cancer cells." (PMID 36010677, 2022). "SALL4 dependency was observed in most of the cancer cell types with the highest dependency score for peripheral nerves system cancers and blood malignancies." (PMID 36010677, 2022). "It has been demonstrated that hypomethylating agents (HMA) which are currently used to treat various types of cancers, activate SALL4 through DNA demethylation as a probable side effect." (PMID 36010677, 2022). "Due to high expression of SALL4 in cancer cells and its silence in almost all adult tissues, it is an ideal target for cancer therapy." (PMID 36010677, 2022). "Various studies have shown that SALL4 significantly dysregulates the Wnt/β-catenin signaling pathway in cancers." (PMID 35216168, 2022). "The Cancer dependency map (Depmap) data, which aim to identify key essential genes in cancer using high-throughput analysis of CRISPR and shRNA, were analyzed by depmap package, R software to assess the essentiality of SALL4 for cancer cells." (PMID 36010677, 2022). "To expand the scope of SALL4 targeted therapy in cancer, we explored a sequential combination therapy approach recently." (PMID 36010677, 2022). "SALL4 overexpression is found in several cancer tissues and hematologic malignancies, suggesting a key role of SALL4 in cancer onset and progression." (PMID 36010677, 2022). "Further optimization of this peptide led to the discovery of FFW, a pre-clinical prototype, and an SALL4/RBBP4 inhibitor that can induce apoptosis in cancer cells and hindrance of formation of xenograft in mice." (PMID 36010677, 2022). "In our cancer model, we found that a high SALL4 expression increases the expression of NuRD complex units, including RBBp4." (PMID 36362083, 2022). "To assess the potential role of RBBp4 in cancer of HER2+ BC progression due to interaction with SALL4 in HER2+ BC, we analyzed RBBp4 expression in BC patient samples from public databases." (PMID 36362083, 2022). "Considering the critical role of SALL4 in cancer cell survival besides the difference in the expression of SALL4 in healthy and cancer cells, this protein seems to be a key target for cancer treatment." (PMID 36010677, 2022). "CIRSPR data showed that SALL4 is an essential driver node with an overall dependency score of −0.13325 among 789 different cancer cell lines." (PMID 36010677, 2022). "SALL4 is a TF that plays essential roles during embryonic development and has also been shown to be involved in various cancer-related processes such as cell proliferation, EMT, maintaining stemness, drug resistance, metastasis, invasion and migration." (PMID 36362083, 2022). "As matter of fact, HDACi has been shown to have promising therapeutic effects on SALL4 expressing cancer cells." (PMID 36010677, 2022). "On the other hand, targeting SALL4 can be specific for cancer cells in which SALL4 gene is reactivated and highly expressed, without toxic effects to adjacent normal tissues that do not express SALL4." (PMID 36010677, 2022). "GSEA analysis suggested that the SALL4 upregulated the GO and pathway of growth and cancer development and downregulated metabolization pathway." (PMID 35692499, 2022).
cancer (continued). "On the other hand, various reports show tight relation of SALL4 to cancer occurrence and metastasis." (PMID 36010677, 2022). "Studies in cancer also indicated that overexpression of SALL4 can increase the proliferation, migration, and invasion of cancer cells through targeting epithelial mesenchymal transition (EMT)." (PMID 35090523, 2022). "The SALL4 expression in adjacent normal mucosa tissues and carcinoma tissues of patients with COAD was detected through bioinformatic analysis based on TCGA database and immunohistochemistry." (PMID 35692499, 2022). "SALL4 staining was localized to the nucleus of cancer cells, and only diffuse nuclear staining was considered positive for SALL4." (PMID 33644042, 2021). "SALL4 re-expression has been observed in different types of human cancers and is regarded as an important biomarker." (PMID 34573282, 2021). "Previously, Sall4 has been described as a “star” factor that links between stem cells, development, and cancer, and amounts of regulators, partners and targets of SALL4 were identified." (PMID 33144328, 2021). "The binding of SALL4 to chromatin and epigenetic modifier enzymes and the resulting epigenetic rewiring of target genes has previously been shown in ESCs as well as in cancer." (PMID 34417458, 2021). "In this systematic review, we summarize the current knowledge of SALL4 and miRNAs functions in development and cancer." (PMID 34573282, 2021). "The core regulatory network for embryonic stem cell maintenance and self-renewal OCT4, SOX2, KLF4, NANOG, and SALL4 are abnormally expressed in human tumor samples suggesting the presence of cancer stem cells." (PMID 34249759, 2021). "SALL4 re-expression has been observed in different types of human cancers, and dysregulation of SALL4 contributes to the pathogenesis, metastasis, and even drug resistance of multiple cancer types." (PMID 34573282, 2021). "Then, using The Cancer Genome Atlas (TCGA) data, we explored the regulation of SALL4 gene expression by analyzing the correlation between DNA copy number variation (CNV) and aberrant SALL4 mRNA expression in GC." (PMID 33644042, 2021). "Most of the studies have focused on the functional relationship of NuRD with SALL1 or SALL4 in development and cancer." (PMID 34944911, 2021). "We focus on members of miRNAs that target SALL4, with particular attention to the emerging roles of the Let-7/Lin28 axis in SALL4 regulation in the context of normal development and cancer." (PMID 34573282, 2021). "Another study compared SALL4 levels between patients prior to adjuvant chemotherapy and found higher SALL4 expression in patients with recurrent cancer when compared with those who were disease-free." (PMID 34573282, 2021). "Pharmacological peptides that exclusively target cancer cells expressing SALL4 were tested as potential cancer therapeutic agents." (PMID 34944911, 2021). "The HDAC-1 and -3 inhibitor Entinostat was identified as a potential treatment for SALL4-expressing cancers." (PMID 34944911, 2021). "Approximately half of the cancer cells in the giant tumor were immunoreactive for SALL4 and some were AFP-positive." (PMID 34792649, 2021). "Since such genes are not expressed in adult tissues except for malignant lesions, factors such as SALL4 represent ideal targets for cancer diagnosis and disease treatment." (PMID 34417458, 2021). "SALL4 is responsible for the transformation, survival, metastasis, and drug resistance of cancer cells." (PMID 35008527, 2021). "The SALL4 involved in the proliferation of cancer was also found to be overexpressed within subtype I." (PMID 34234737, 2021). "In this review, we summarize current knowledge of the interaction between SALL4 and miRNAs in mammalian development and cancer, paying particular attention to the emerging roles of the Let-7/Lin28 axis." (PMID 34573282, 2021).